TCF4 (transcription factor 4)
Diseases named in the same sentence as TCF4 in open-access papers (continued):
Sharing a sentence is not in itself a finding about the gene and the disease.
liver cancer (15 papers, 2012 to 2024). An epithelial or non-epithelial malignant neoplasm that arises from the liver. "Mechanistically, TRIB2 enhances nuclear co-accumulation of β-TrCP E3 ligases and β-catenin, promoting the destabilization of β-catenin and TCF4 in liver cancer." (PMID 37686524, 2023). "We examined blood samples from HBL patients with active β-catenin-TCF4 pathways in primary liver cancer and discovered GPC3 and AFP in their bloodstream." (PMID 36551548, 2022). "TRIB2 is also specifically regulated by Wnt signaling in liver cancer cells, which is associated-Ub E3 ligase-TrCP, RFWD2, and Smurf1 reducing TCF4/β-catenin expression." (PMID 34646775, 2021). "TRIB2 is specifically activated by Wnt pathway effectors TCF4 and β-Catenin in the human liver cancer cell line HepG2." (PMID 34070799, 2021). "In addition, TRIB2 contributes to the negative regulation of WNT/β-catenin/TCF4 signaling specifically in liver cancer cells by physically binding to β-TrCP, COP1, and SMAD ubiquitination regulatory factor 1 (SMURF1)." (PMID 37686524, 2023). "Furthermore, MEG3 overexpression decreased the interaction between β-catenin and LEF, TCF4 in liver cancer cells." (PMID 29449541, 2018). "To explore whether MEG3 influenced β-catenin activity, we analyzed the activity of β-catenin co-activators LEF and TCF-4 in liver cancer cells." (PMID 29449541, 2018). "Therefore, to determine whether Wnt/β-catenin signaling is implicated in hepatocarcinogenesis, we examined the expression of Wnt/β-catenin signaling components, including Wnt1, LEF, and TCF4, in tissue samples from liver cancer patients." (PMID 26967248, 2016). "VGLL4 interrupts YAP/TEAD4 complex in liver cancer and TEAD/TCF4 (Transcription Factor 4) complex to suppress Wnt/β-catenin downstream targets." (PMID 35602596, 2022). "The AFP data from pathology reports revealed that HBL patients with an active β-catenin-TCF4-CEGRs/ALCDs pathway had high levels of AFP protein in their serum samples, consistent with other reports that increased AFP is a signature of liver cancer." (PMID 36551548, 2022). "The Wnt/β-catenin/TCF4 pathway promotes TRIB2 expression in liver cancer cells, and in this case TRIB2 also produces a negative feedback, via TRIB2-mediated ubiquitination and degradation of TCF4 and β-catenin through the E3 ligase binding region." (PMID 34070799, 2021). "To determine whether JMJD2D could interact with β-catenin/TCF4 and NICD1 in liver cancer cells, we performed Co-IP assays." (PMID 33434575, 2021). "In this regard, the expression of EpCAM, a putative liver cancer stem cell (CSC) marker and a β-catenin/TCF-4 downstream target gene product, was not upregulated in these cells." (PMID 22768190, 2012).
developmental delay (14 papers, 2015 to 2025). "We identified TCF4 mutations in two children with severe developmental delay and facial features later confirmed to be in keeping with Pitt–Hopkins syndrome (cases 67 and 69)." (PMID 26993267, 2016). "TCF4 codes for a transcription factor; both common and rare variants have been implicated in the etiology of SZ, BD, ASD, and developmental delay." (PMID 28321286, 2017).
osteoarthritis (14 papers, 2012 to 2025). A noninflammatory degenerative joint disease occurring chiefly in older persons, characterized by degeneration of the articular cartilage, hypertrophy of bone at the margins and changes in the synovial membrane. "This study was to investigate the underlying mechanism by which Saikosaponin D (SSD) mitigates the inflammatory response associated with osteoarthritis (OA) and regulates autophagy through upregulation of microRNA (miR)-199-3p and downregulation of transcription Factor-4 (TCF4)." (PMID 38389105, 2024). "Downregulation of lncRNA MFI2-AS1 reduced LPS-mediated osteoarthritis progression via impacting the miR-130a-3p/TCF4 axis." (PMID 37779916, 2023). "Silencing of lncRNA KCNQ1OT1 blocked the progression of osteoarthritis via changing the miR-211–5p/TCF4 axis." (PMID 37779916, 2023). "A recent study reported that miR-137 is downregulated in LPS-induced chondrocytes and articular cartilage samples, and miR-137 reverses the development of osteoarthritis (OA) by targeting the suppression of TCF4 via the AMPK/NF-κB signaling pathway." (PMID 35236255, 2022). "Circ‐IQGAP1 promotes IL‐1β‐induced chondrocyte apoptosis, inflammation, and extracellular matrix degradation by miR‐671‐5p/TCF4 axis in osteoarthritis." (PMID 33675175, 2021). "Whereas, chondrocyte apoptosis in osteoarthritis was induced by elevated TCF-4 mRNA expression through NF-κB signaling." (PMID 30379886, 2018). "Hexachlorophene also exhibited suppressive effects on TCF4/β-catenin transcriptional activity in a concentration-dependent manner of human bone marrow mononuclear cells obtained from a patient with osteoarthritis under informed consent." (PMID 26553591, 2015). "miRNA-137 is reportedly implicated in various diseases; a previous report suggested that miR-137 is downregulated in LPS-induced chondrocytes and articular cartilage samples, and that miR-137, via the AMPK/NF-κB signaling pathway, prevents TCF4 from reversing the progression of osteoarthritis." (PMID 35236255, 2022). "All in all, we propose for the first time that miR-137 can reverse the disease process of osteoarthritis through targeted inhibition of TCF4-mediated AMPK/NF-κB signaling pathway, which may become a new direction for the treatment and prevention of OA." (PMID 32432314, 2020). "To determine whether changes in the Wnt-signaling pathway are associated with osteoarthritis, we evaluated the expression levels of Wnt transcription factors, LEF-1 and TCF-4, and phospho-β-catenin in osteoarthritic and normal articular chondrocytes." (PMID 22513174, 2012). "In rat cartilage tissue of osteoarthritis, miR-137 is also downregulated, and its over-expression can reduce the inflammatory factors (TNF-α, IL-1β, IL-6) via downregulating the TCF4-AMPK/NF-κB pathway." (PMID 38138985, 2023). "Immunohistochemical and qRT-PCR analysis of β-catenin, TCF-4, and SOST/Wise revealed an elevated expression of β-catenin and TCF-4 in the intermediate and late stages of osteoarthritis, whereas sclerostin levels were lower compared to levels in the early-stage osteoarthritis samples." (PMID 31546898, 2019).
microcephaly (13 papers, 2015 to 2023). A congenital or acquired developmental disorder in which the circumference of the head is smaller than normal for the person's age and sex. "Among them, two members, MYCN and TCF4, will be highlighted here for their association with microcephaly." (PMID 38094004, 2023). "Mutations in DYRK1A and TCF4 cause syndromic diseases presenting with microcephaly and intellectual disability." (PMID 28733602, 2017). "Tcf4 binds together with microcephaly-associated transcription factors Smad4, Sox2, Chd7 and Ep300 to active enhancers at primary microcephaly genes Mcph1 and Wdr62." (PMID 28375211, 2017). "Moreover, Tcf4 protein interacts with 10 transcriptional regulators associated with microcephaly, including Smad4." (PMID 28375211, 2017). "Tcf4 binds with a number of its interaction partners to primary microcephaly genes and (at least) Tcf4 and Smad4 also regulate such genes, providing an explanation for their shared microcephaly phenotype." (PMID 28375211, 2017). "Thus, our data suggest that embryonic reinstatement of Tcf4 expression could prevent microcephaly in PTHS model mice." (PMID 35535852, 2022). "Mutations in TCF4 have been associated with Pitt–Hopkins syndrome (PTHS), which is characterized by severe ID, delayed motor development, seizures, wide mouth and distinctive facial features, hypotonia, microcephaly, limited walking abilities, and intermittent hyperventilation followed by apnea." (PMID 31409060, 2019).
type 2 diabetes (13 papers, 2009 to 2025). "Variants in the transcription factor-7–like 2 (TCF7L2/TCF4) gene, involved in Wnt signaling, are associated with type 2 diabetes." (PMID 29967064, 2018). "The interest in Tcf7l2 (also known as Tcf4) is recently heightened as it is thought to be significantly linked to type II diabetes, which is characterized, by insulin resistance and changes in glucose metabolism, especially in muscle." (PMID 23251550, 2012). "1,25(OH)2D3 has also been implicated in a protective role against type 1 and type 2 diabetes, and the regulation of TCF-4 we show here may play a role in disease establishment, progression, and treatment." (PMID 19924301, 2009). "Of note, mutations in subtype-defining transcription factors, including HNF1A, TCF4, NEUROD1 and HNF4A, cause MODY, and their cis-regulatory sites map to type 2 diabetes risk loci." (PMID 40768044, 2025). "The answer lies in the well-known type 2 diabetes marker, TCF4 also known as TCF7L2 (transcription factor 7-like 2)." (PMID 37215099, 2023). "It is interesting to note that TCF4, a transcription factor, coded by TCF7L2, the most strongly associated and replicated type 2 diabetes susceptibility loci, is an integral part of Wnt-1 signaling." (PMID 20625434, 2010). "The role of STRA6 in type 2 diabetes and its regulation by TCF4 are currently under investigation in our laboratory." (PMID 20625434, 2010). "In vitro experiments showed that high glucose toxicity inhibited GLP-1 secretion by enteroendothelial cells and suppressed β-catenin and TCF7L2 levels, suggesting an important role for TCF4 (TCF7L2) in glucose homeostasis and type 2 diabetes development (Hong J.-H." (PMID 40129942, 2025). "In addition, we discovered seven other potential key transcriptional regulators of gene expression networks in type 2 diabetes: Etv1, Irx1 and Foxp1 (alpha cells); Ehf, Hhex and Tcf4 (delta cells); and Zfhx3 (macrophages)." (PMID 39508880, 2025).
bipolar disorder (12 papers, 2017 to 2025). A disorder of the brain that causes unusual shifts in mood, energy, activity levels and the ability to carry out day-to-day tasks. "Apart from MDD, TCF4 has also been associated with other psychiatric and neurological disorders, such as bipolar disorder and post-traumatic stress disorder." (PMID 36011346, 2022). "Due to molecular interrogation of a locus on chromosome 18 and its association with bipolar disorder, a CTG trinucleotide repeat was discovered in TCF4 and subsequently named CTG18.1." (PMID 32735996, 2021). "The CTG trinucleotide repeat (TNR) expansion in Transcription factor 4 (TCF4) intron 3 is the main cause of Fuchs’ endothelial corneal dystrophy (FECD) and may confer an increased risk of developing bipolar disorder (BD)." (PMID 33116252, 2020). "In addition, genes linked to ID (TCF4, CPLX1, CDK6, KDM5B), ASD (RORA, KDM5B), and bipolar disorder (ZNF804A) were also among the 16 differentially expressed target genes." (PMID 29665782, 2018).
colorectal tumor (12 papers, 2005 to 2025). "Our study shows that Tcf4 plays a crucial role in regulating secretory cell fate and antimicrobial peptide production in both healthy intestinal epithelium and colorectal tumors." (PMID 40221753, 2025). "The functional β-catenin-TCF4 complex β-catenin has been found to directly upregulate Bambi in colorectal tumor cells." (PMID 39684392, 2024). "And silencing TCF4 reduced proliferation, invasion, and metastasis of colorectal tumor cells, and slowed the growth of xenograft tumors in nude mice, reducing tumor weight, Ki-67 growth index, and tumor CD31-positive neovascularisation." (PMID 37337284, 2023). "For instance, in addition to the induction of the MCC protein, β-catenin/TCF4-induced SRSF3 expression decreased Rac1b expression in colorectal tumor cells by increasing skipping of alternative exon 3b." (PMID 33072610, 2020). "To determine the significance of p-c-Jun, TCF4 and β-Catenin in human colorectal tumors, we analyzed the nuclear expression of these proteins in resected colorectal tumors by immunohistochemistry." (PMID 18992165, 2008). "Furthermore, we found that the activation of ER stress by oridonin was attenuated by overexpression of TCF4, which further reduced the inhibitory effect of oridonin on the colorectal tumor." (PMID 37337284, 2023). "In summary, we found LEF-1 expression in 26% and TCF4 in 46% of colorectal tumours." (PMID 21092222, 2010). "Furthermore we obtained evidence for a role of LEF-1 and TCF4 as independent prognostic variables of clinical outcome in colorectal tumour patients." (PMID 21092222, 2010). "However, only a few studies have examined c-Jun, TCF4 and β-Catenin expression in human colorectal tumors." (PMID 18992165, 2008). "In this study, we demonstrated that expression of HOXB13 is frequently diminished in colorectal tumours to confer a positive growth signal, which may be accomplished thorough the regulation of β-catenin/TCF4 signals." (PMID 15928669, 2005). "However, CD97 mRNA expression levels were not affected by TCFs, as determined in inducible dominant-negative TCF colorectal tumor cell lines, and co-expression of WT or S33A-mutated β-catenin with TCF-4 did not enhance CD97 promoter activity." (PMID 29888202, 2018). "Colorectal tumor apoptotic cells are characterized by AMP-activated protein kinase (AMPK) signaling cascade activation, activation of the pro-apoptotic caspase-3 and an altered expression pattern of β-catenin and transcription factor 4 (TCF-4) that blocks their interaction." (PMID 30487390, 2018). "However, expressions of p-c-Jun in combination with TCF4 and β-Catenin have not been explored with regard to human colorectal tumors." (PMID 18992165, 2008).
adenoma (11 papers, 2008 to 2025). A neoplasm arising from the epithelium. "In Tcf4-deficient adenomas, we observed a significant decrease in the number of tdTomato-positive glandular structures." (PMID 40221753, 2025). "In APC-deficient adenoma, accumulation of β-catenin complexed with nuclear TCF4 results in the increased expression of its oncogenic target genes, such as cyclin-D1 that promotes intestinal cell proliferation and polyp formation." (PMID 26500891, 2015). "The coupling of oncogenic RAS to deregulated WNT leads to the formation of a large adenoma, as βcat/TCF4 and MYC are complemented by AP-1 of RAS." (PMID 35159051, 2022). "Nuclear expression of p-c-Jun, TCF4 and β-Catenin was compared among the adenomas, HGINs and adenocarcinomas." (PMID 18992165, 2008). "Expression of p-c-Jun, TCF4 and β-Catenin were significantly higher in adenomas than in the adjacent normal epithelia." (PMID 18992165, 2008). "In the tumor cells of adenomas, HGINs and adenocarcinomas, staining for p-c-Jun was mainly detected in the nucleus, while staining was observed in the nucleus and cytoplasm for TCF4, and in the nucleus, cytoplasm and cellular membrane for β-Catenin." (PMID 18992165, 2008). "p-c-Jun expression, but not TCF4 and β-Catenin, was higher in adenomas and HGINs than in adenocarcinomas, in which p-c-Jun expression was negatively correlated with pT stage progression." (PMID 18992165, 2008). "The importance of c-Jun in colorectal adenoma formation, through its interaction with β-catenin and TCF4, has been demonstrated in animal models, but Wnt/PCP signalling is not the only route to c-Jun activation and its contribution to this in adenomas warrants further investigation." (PMID 18414471, 2008). "Interestingly, we found that the nuclear expression of TCF4 is significantly higher in adenomas than in the adjacent normal epithelia." (PMID 18992165, 2008). "Interestingly, immunohistochemical studies performed on four papillary thyroid carcinomas and three normal thyroid tissues taken at distance of benign adenoma showed a TCF-4 and TTF-1 positive expression and localized in nuclei in normal tissue as well as in PTC." (PMID 21814573, 2011).
glioblastoma (11 papers, 2013 to 2025). The most malignant astrocytic tumor (WHO grade IV). "For instance, exosomal circ-AHCY recruited EIF4A3 to stabilize TCF4 mRNA and facilitated glioblastoma cell growth via the Wnt signaling pathway." (PMID 39858034, 2025). "The up-regulation of FZD6 coupled with down-regulation of the transcription factor TCF4 was previously proposed to predict the low survival of glioblastoma patients." (PMID 33630973, 2021). "In glioblastoma, sulforaphane suppresses the activity of transcription factor 4 (TCF4), a downstream factor of Wnt/β-catenin signaling, thereby reducing the levels of miR-21." (PMID 33066509, 2020). "There was less information available for these mutual feedback regulatory axis; one study showed that regulation of EZH2 was involved in positive feedback loop with β-catenin/transcription factor 4 (TCF4) and Stat3 signaling in glioblastoma cells." (PMID 28360411, 2017). "Our data suggest that Bcl-w-induced invasion of glioblastoma cells is related to the β-catenin/TCF-4 pathway that acts as a downstream regulator of PI3K and Akt." (PMID 23826359, 2013). "We also investigated β-catenin/TCF4-mediated NRF3 regulation in other human cancer cell lines: DLD-1 (colorectal adenocarcinoma), H1299 (non-small cell lung carcinoma), A172 (glioblastoma) and HeLa (cervical epithelioid carcinoma)." (PMID 31288376, 2019). "Based on these data, we suggest that Bcl-w regulates positively nuclear β-catenin translocation and its binding to TCF-4 in the nucleus, in turn, stimulating the expression of target genes, such as MMP-2 to promote migration and invasiveness in U251 glioblastoma cells." (PMID 23826359, 2013). "In glioblastoma (GBM) and anaplastic astrocytomas, WNT signaling is misregulated and both β-catenin and the transcription factor 4 (TCF4) show abnormal expression levels; in particular, increased nuclear amount of β-catenin are found in those patients presenting the mesenchymal type of GBM." (PMID 29261132, 2017).
leukemia (11 papers, 2008 to 2025). A malignant (clonal) hematologic disorder, involving hematopoietic stem cells and characterized by the presence of primitive or atypical myeloid or lymphoid cells in the bone marrow and the blood. "The leukemia-associated Mllt10/Af10 and its partner the histone methyltransferase Dot1l are identified as Tcf4/β-catenin co-activators and shown to be essential for Wnt-driven endogenous gene expression, intestinal development and homeostasis." (PMID 21103407, 2010). "We thus identified the leukemia-associated Mllt10 (Af10) as an interactor of the Tcf4 complex in the crypt proliferative compartment." (PMID 21103407, 2010). "In this study, using a proteomics approach, we identify the leukemia-associated Mllt10/Af10 and its partner the histone methyltransferase Dot1l as interactors with Tcf4/β-catenin in the mouse small intestinal epithelium." (PMID 21103407, 2010). "Using proteomics, we identified the leukemia-associated Mllt10/Af10 and the methyltransferase Dot1l as Tcf4/β-catenin interactors in mouse small intestinal crypts." (PMID 21103407, 2010). "Herein, artesunate (ART) induced ER stress in leukaemia cells, resulting in eIF2α phosphorylation, activation of transcription factor 4, subsequent CHOP upregulation and XBP1 splicing." (PMID 35845184, 2021).